APOE (apolipoprotein E)
Diseases named in the same sentence as APOE in open-access papers (continued):
Sharing a sentence is not in itself a finding about the gene and the disease.
breast carcinoma (continued). "Although previous studies reported the presence of a ε4 allele that positively mediated the incidence of breast cancer, the currently available literature on associations between APOE polymorphism and breast cancer and breast cancer chemotherapy risk is inconsistent." (PMID 36765598, 2023). "The apoE plasma concentration was also positively associated with breast cancer malignancy." (PMID 35268435, 2022). "In addition, APOE polymorphisms also mediate the incidence of breast cancer, colorectal cancer, prostate cancer, gastric cancer, endometrial carcinoma, pituitary adenoma, and head and neck cancer." (PMID 36057714, 2022). "A meta-analysis evaluating the APOE gene in breast cancer patients identified one and a half times increased risk of breast cancer among Asians carrying the e4 protein isoform of APOE, supporting this allele as a low-penetrant risk factor for development of breast cancer." (PMID 33731765, 2021). "APOE ε2 polymorphisms may protect against CRCD in older breast cancer survivors receiving chemotherapy." (PMID 33748669, 2021). "This hypothesis-generating study aimed to examine the association of APOE ε4 status and treatment exposures with cognitive function in breast cancer survivors." (PMID 34480030, 2021). "For example, apoD and apoE in serum are viewed as risk factors for breast carcinoma." (PMID 32306242, 2020). "APOE ε4 allele is found to be a low-penetrant risk factor for development of breast cancer." (PMID 25029444, 2014). "APOE genotypes has been reported implicated in the breast cancer." (PMID 25029444, 2014). "The APOE ε4 allele appears to be associated with an increased risk of gallstones and breast cancer." (PMID 25029444, 2014). "However, APOE has not featured strongly in breast cancer GWAS to date, so the extent of genetic risk afforded by APOE in breast cancer may still be weak." (PMID 40149482, 2025). "In addition, the genetic risk for breast cancer, the APOE ε4 genotype, is associated with the increased expression of amyloid ß (Aß) and tau may trigger the neuropathology of AD." (PMID 36765598, 2023). "Therefore, elevated blood APOE levels may be used to monitor the risk of lymphedema in breast cancer survivors." (PMID 34873574, 2021). "In breast cancer, APOE overexpression activates PI3K/Akt signaling to drive tumor growth and metastasis." (PMID 41390817, 2025). "The measurement of ApoE levels has been proposed as a marker for identifying breast cancer patients and monitoring disease progression." (PMID 40149482, 2025). "APOE exerts biological functions during certain female fertility disorders (endometriosis) and other gynecological diseases (such as breast cancer, choriocarcinoma, endometrial adenocarcinoma/hyperplasia, and ovarian cancer)." (PMID 39650066, 2024). "Our results indicate that Cd68+Cd74+ApoE+ macrophages play a crucial role in breast cancer metastasis to the lungs." (PMID 39695088, 2024). "Third, our APOE studies focused on female mice given the connections between CICI and APOE in breast cancer survivors; future studies should include male mice, given the broader use of doxorubicin in other types of cancers." (PMID 37944881, 2024). "Meanwhile, PPI analysis showed that APOE and STAT3 seem to play a pivotal role in all proteins and are strongly associated with the development of breast cancer." (PMID 38887235, 2024). "We noticed that some other researchers had worked on the TAM population in human breast cancer, which was defined by APOE, APOC, and C1Q expression." (PMID 36814925, 2023). "Single-cell analysis in breast cancer has also shown that SPP1-positive TAMs express high levels of apolipoprotein E (APOE), CD204, CD68, and CADM1." (PMID 37190178, 2023). "Consistent with our findings, Ben pointed out that especially in breast cancer, APOE can inhibit the proliferation and migration of tumor cells by regulating cholesterol metabolism, and APOE can be used as a target to improve prognosis." (PMID 35371313, 2022).
breast carcinoma (continued). "The protein expression of APOE in the tumor group was decreased for breast cancer, colon cancer, renal cell cancer, ovarian cancer, endometrial cancer, HNSC, and lung adenocarcinoma, compared to their normal tissues." (PMID 37304007, 2022). "APOE total protein is significantly heightened in the primary tissues of some cancers, including breast cancer, colon cancer, ovarian cancer, UCEC, and LUAD (as shown in Suppl." (PMID 37304007, 2022). "Some scholars pointed out that the expression level of APOE in the serum of breast cancer patients increased significantly, and these patients were more prone to metastasis." (PMID 35371313, 2022). "As APOE ε4 is present in only a minority of the population, our sample of APOE ε4+ breast cancer survivors is correspondingly small and precluded examining important sub-populations." (PMID 34480030, 2021). "Initial studies of the effect of APOE ε4 on cognitive outcomes in breast cancer have been inconclusive." (PMID 34480030, 2021). "To better understand the mechanism by which cholesterol regulates tumor progression, we expressed apoA-I and apoE in the human breast cancer cell lines MCF-7 and MDA-MB-231." (PMID 32321558, 2020). "Our study demonstrates for the first time that apoA-I and apoE expression in two different types of human breast cancer cell lines can have very different consequences on the cancer properties of these cell lines." (PMID 32321558, 2020). "APOE is estimated to account for 20% of the AD attributable risk, and the APOE-associated risk is similar to those identified for major genes in other Mendelian diseases, such as BRCA1 in breast cancer." (PMID 30982098, 2019). "ApoE KO mice showed increased tumor development and pulmonary metastases in a mammary cancer cell orthograft model and in B16F10 mouse melanoma metastasis in comparison to WT mice." (PMID 31275318, 2019). "Recent studies revealed that ApoE KO mice showed much greater orthotopic mammary tumor development and pulmonary metastases than WT mice." (PMID 31275318, 2019). "ApoE knock-out mice disclose increased mammary tumor incidence, likely in relationship with their hyperlipidemic state." (PMID 23372804, 2013). "With 2D-nanoLC-MS/MS, afamin, apolipoprotein E and isoform 1 of inter-alpha trypsin inhibitor heavy chain H4 (ITIH4) were found to be higher in pre-diagnostic breast cancer (p < 0.05), while alpha-2-macroglobulin and ceruloplasmin were lower (p < 0.05)." (PMID 21871081, 2011). "Notably, ApoE was also shown to affect tumor dynamics in its modulation of breast cancer cell proliferation and differentiation." (PMID 40149482, 2025). "Alongside this, phosphorylation of APOE at the S147 locus is decreased in these cancers, differing to controls in ovarian and breast cancers, although the mechanistic relevance remains unclear." (PMID 40149482, 2025). "As with PCa and breast cancer, ApoE has been proposed as a prognostic factor in CRC." (PMID 40149482, 2025). "Furthermore, upon isolating macrophages and Ly6g+ neutrophils from lungs with 4T1 breast cancer metastasis, we found that macrophages expressed higher levels of ApoE, S100A10, and S100A4 than those macrophages isolated from normal mice." (PMID 39695088, 2024). "Alteration of ApoE glycosylation profiles observed in preeclampsia and breast cancer could indicate that ApoE glycosylation status might also be a distinguishing feature in other gynecological diseases." (PMID 39169951, 2024). "ApoE has been reported to play a role in the development of breast cancer." (PMID 39695088, 2024). "As APOE ε4 is only present in a small percentage of the population, the low sample size of APOE ε4 breast cancer patients may result in differences and limitations, and the substantial selection bias would also influence the direction of the association." (PMID 36765598, 2023).
breast carcinoma (continued). "Another longitudinal study showed that breast cancer survivors with the APOE ε4 allele had no significant worsening of cognitive function over time and no vulnerability to chemotherapy exposure." (PMID 36765598, 2023). "Several loci that are previously well known as associated with the risk of the diseases have been identified in our study, such as the loci LPA and CELSR2 for IHD48,49, FGFR250 and CASC1651 for breast cancer, MYOC52 and TMCO153 for glaucoma, and APOE e4 variant for AD54." (PMID 36114182, 2022). "The variability of ApoE glycosylation observed in gynecological diseases such as preeclampsia and breast cancer clearly indicate that the degree of ApoE glycosylation may be also taken into account as a differentiating factor in some gynecological diseases." (PMID 34281251, 2021). "Most prior genetic studies of CRCD in breast cancer survivors have focused on APOE ε4." (PMID 33748669, 2021). "Alterations in ApoE glycosylation have been observed in the course of diseases such as preeclampsia or breast cancer, but little is known about the characteristics of ApoE glycans analyzed in human seminal and blood serum/plasma in the context of male reproductive health." (PMID 34281251, 2021). "Patients with breast cancer are distinguished by methylation and hydroxylation patterns of APOE, which may contribute greatly in breast cancer progression." (PMID 34588485, 2021). "For example, the effect of APOE ε4 allele was first observed in breast cancer and lymphoma survivors, but similar associations have not been replicated in similar patient populations and cognitive domains." (PMID 30382534, 2019). "Furthermore, we collected breast cancer LN tissues and conducted mIF staining, which showed that in LN tissues with metastasis, APOE+ macrophages and CD8+ exhausted T cells were in close proximity, whereas in those without LN metastasis, these two subpopulations were sparsely distributed." (PMID 40492378, 2025). "However, the study identified a previously unknown O-glycosylation site at Ser129 on plasma ApoE, and the degree of glycosylation of this residue was found to be slightly increased in breast cancer samples compared to healthy controls." (PMID 39169951, 2024). "The scRNA‐seq analysis of 26 primary breast cancer samples identified several macrophage clusters associated with M1‐like markers (CXCL10), two distinct clusters associated with M2‐like markers (EGR1 and SIGLEC1), and two distinct clusters associated with lipid markers (FABP5 and APOE)." (PMID 38426622, 2024). "Likewise, in Taiwan, studies reported a risk of breast cancer in females with the APOE genotype; neither the APOE2 nor APOE4 alleles showed a notable correlation with markers of cell growth." (PMID 38067270, 2023). "Additionally, researchers have documented contradicting reports between APOE polymorphisms and breast cancer risk; while some studies have reported an association, other studies did not report any link between APOE polymorphism and breast cancer risk." (PMID 38067270, 2023). "Moreover, has been APOE positively correlated with breast cancer progression and invasion." (PMID 38067270, 2023). "On the cellular level, apoE may inhibit angiogenesis and the proliferation of breast cancer cells." (PMID 35268435, 2022). "Although the protein expression levels of APOE cannot be predicted from the mRNA level of APOE directly, the decreased protein expression levels of APOE were regulated in female-dominant cancer types, such as breast cancer, ovarian cancer, and UCEC (as shown in Suppl." (PMID 37304007, 2022). "However, the relationship between breast cancer and ApoE in humans is still under debate, and ApoE may impact disease susceptibility or response to therapy." (PMID 23372804, 2013).
breast carcinoma (continued). "Of the proteins detected with 2D-nanoLC-MS/MS, afamin, apolipoprotein E and an isoform of ITIH4 were slightly, but significantly higher and alpha-2-macroglobulin and ceruloplasmin slightly, but significantly lower in pre-diagnostic breast cancer samples compared to control samples." (PMID 21871081, 2011). "Meanwhile, inhibition of ApoE expression in THP-1 cells blocked the CD86 downregulation and the CD163 upregulation induced by breast cancer cells." (PMID 39695088, 2024). "Additional scRNA‐seq data from human breast cancer identifies a monocyte‐derived macrophage population expressing TREM2, SPP1, C1QA, and APOE." (PMID 38426622, 2024). "The density of FOLR2+ macrophages in tumors has been correlated with survival in breast cancer and HCC patients; therefore, the significant role we observed for Macro_FOLR2 + APOE+, and its interaction with T cells, is notable." (PMID 39034339, 2024). "Approximately 30% more cells of the macrophage subtypes positive for LAM2_APOE, LAM1_FABP5 and EGR1, respectively, expressed CLEC10A in TNBC in comparison with ER+ / HER2+ breast cancer (Chi-squared p < 0.001)." (PMID 38206856, 2024). "We compared the phosphorylation levels of APOE in primary tumor tissue and their matched normal tissue by CPTAC for three types of tumors: breast cancer, ovarian cancer, and UCEC." (PMID 37304007, 2022). "Common plasma proteins including APOE, ITIH4 and C3 showed significantly different intensity between breast cancer versus ovarian cancer and normal plasma." (PMID 31889940, 2019). "AGR2, APOE, AQP3, and CD99L2 may be of particular interest for the epithelial differentiating action exerted by circDOCK1-1 in TNBC-mes breast cancer cells." (PMID 34771489, 2021). "To fill this clinical gap, we conducted an evaluation of the role of APOE ε2 in longitudinal cognitive function among older breast cancer survivors and a matched noncancer control group in the Thinking and Living with Cancer (TLC) study." (PMID 33748669, 2021). "Intriguingly, ApoE physically interacts with HCCR-1, an onco-protein that promotes breast cancer." (PMID 23372804, 2013). "To analyze whether breast cancer cells enhanced ApoE expression in macrophages or not and to determine the impact of ApoE on macrophage function, we utilized a THP-1/Hs578T TNBC co-culture model and assessed the effects of ApoE on the macrophage phenotype by blocking." (PMID 39695088, 2024). "In this follow-up study of 80 chemotherapy-treated breast cancer survivors and 80 non-cancer controls, we evaluated additional factors to help explain biotype expression: neurofunctional stability, brain age, apolipoprotein (APOE) genotype, and psychoneurologic symptoms." (PMID 37127832, 2023).
Lewy body dementia (66 papers, 2016 to 2025). A progressive form of dementia characterized by the presence of protein deposits called Lewy bodies in the midbrain and cerebral cortex, and loss of cholinergic and dopaminergic neurons. "The APOE ε4 allele is a significant genetic risk factor for Lewy body dementia and influences the disease’s progression and Lewy-related pathology." (PMID 41185066, 2025). "For example, APOE was previously associated with an increased risk of dementia with Lewy bodies (DLB) and Parkinson’s disease." (PMID 40382659, 2025). "Research has focused on deciphering the function of ApoE in neural β-amyloid deposition to understand why ApoE4 is a risk factor for Lewy body dementia and AD." (PMID 38139244, 2023). "Carriage of the ε4 allele of the APOE gene is an established risk factor for AD and other forms of dementia (dementia with Lewy bodies (DLB), FTD)." (PMID 37160649, 2023). "The APOE ε4 allele is a significant genetic risk factor for sporadic Alzheimer's disease (AD) and dementia with Lewy bodies." (PMID 38026513, 2023). "Among various described genetic risk factors, the ε4 allele of the APOE gene (APOE ε4) confers the strongest genetic risk to develop AD and dementia with Lewy bodies (DLB)." (PMID 37400888, 2023). "The APOE-ε4 allele is not only one of the strongest risk factors for AD but it is also a risk factor for Lewy body dementia." (PMID 35572149, 2022). "The ε4 allele of the APOE gene (APOE4) is a strong genetic risk factor for Lewy body dementia (LBD)." (PMID 36056345, 2022). "What’s more, APOE ε4 allele is a strong risk factor across the Lewy body disease spectrum, and it has been confirmed to be associated with the occurrence of LBD, and can accelerate LBD progression and cause poor prognosis." (PMID 36123648, 2022). "APOE ε4 allele is a strong risk factor across the Lewy body disease spectrum and increases the likelihood of presenting with dementia in the context of even a pure synucleinopathy without co-existent ADP." (PMID 33485373, 2021). "From clinical studies, it is clear that APOE ε4 is also linked with increased risk for dementias across the spectrum of Lewy body diseases, including dementia with Lewy bodies, and PD." (PMID 31331333, 2019). "The most established genetic risk factor for late-onset AD is the APOE ε4 allele, and this is also over-represented in sporadic Lewy body dementias compared with controls." (PMID 29971228, 2018). "Recent work further shows that the presence of the APOE ε4 allele also increases the risk of dementia with Lewy bodies (DLB) whereas carriers of the APOE ε2 allele are protected against developing either of these two disorders." (PMID 28137305, 2017). "APOE ε4 has been found to increase the risk of dementia with Lewy bodies (DLB) and FTD." (PMID 36337698, 2022). "As overexpression of the pathogenic αSyn A53T causatively increases the lipid droplet accumulation in dopaminergic neurons, it is tempting to speculate that apoE loss of function may trigger the vicious cycle between abnormal lipid droplet accumulation and αSyn pathology in Lewy body diseases." (PMID 34453582, 2021). "Although the APOE ε4 is the strongest risk factor for AD, a study of 652 autopsy-confirmed Lewy body disease demonstrated that patients with APOE ε4 had higher Lewy body burden in the cortices, independent of AD pathology." (PMID 41185066, 2025). "Several studies have also reported that APOE ε4 carriers with PD or Lewy body dementia experience more rapid cognitive decline." (PMID 41185066, 2025). "Significant interactions between APOE ε4 and age at death were observed for neuritic plaques, Braak staging, diffuse neuritic plaques, and Lewy body disease pathology, with the effect of APOE ε4 decreasing at older ages." (PMID 40382659, 2025). "Deficits in the lipid handling genes APOE and GBA1 are the most significant genetic risk factors for Lewy body dementia and related dementia syndromes." (PMID 37947642, 2023).